FZD8 (frizzled class receptor 8)
Description:
Receptor for Wnt proteins. Component of the Wnt-Fzd-LRP5-LRP6 complex that triggers beta-catenin signaling through inducing aggregation of receptor-ligand complexes into ribosome-sized signalosomes. The beta-catenin canonical signaling pathway leads to the activation of disheveled proteins, inhibition of GSK-3 kinase, nuclear accumulation of beta-catenin and activation of Wnt target genes. A second signaling pathway involving PKC and calcium fluxes has been seen for some family members, but it is not yet clear if it represents a distinct pathway or if it can be integrated in the canonical pathway, as PKC seems to be required for Wnt-mediated inactivation of GSK-3 kinase. Both pathways seem to involve interactions with G proteins. May be involved in transduction and intercellular transmission of polarity information during tissue morphogenesis and/or in differentiated tissues. Coreceptor along with RYK of Wnt proteins, such as WNT1.
Synonyms: Fz-8; hFz8
Tractability: Antibody: a drug acting on it is in phase 2 or 3 trials; UniProt places it where antibodies can reach, with medium confidence; UniProt predicts a signal peptide or a membrane-spanning region; its Gene Ontology location is reachable by antibodies, with medium confidence. PROTAC: UniProt records ubiquitination sites on it; ubiquitination databases record sites on it. Other modalities: a drug acting on it is in phase 2 or 3 trials.
Target class: Frizzled family G protein-coupled receptor; Membrane receptor
Gene: Protein-coding gene on chromosome 10 (35,638,247 to 35,642,296, reverse strand). Ensembl gene ENSG00000177283.
Subcellular location: Membrane; Golgi apparatus; Cell membrane
Subcellular location (Human Protein Atlas): Endoplasmic reticulum; Primary cilium
Pathways (Reactome):
Signal Transduction: Asymmetric localization of PCP proteins; Class B/2 (Secretin family receptors); Regulation of FZD by ubiquitination
Disease: Signaling by RNF43 mutants
Gene Ontology:
Molecular function: PDZ domain binding; protein binding; ubiquitin protein ligase binding; Wnt receptor activity; Wnt-protein binding; signaling receptor binding; transmembrane signaling receptor activity
Biological process: canonical Wnt signaling pathway; neuron differentiation; non-canonical Wnt signaling pathway; cell surface receptor signaling pathway
Cellular component: membrane; plasma membrane; Golgi apparatus; neuronal dense core vesicle; Wnt-Frizzled-LRP5/6 complex
Genetic constraint (gnomAD): Loss-of-function variants: 17 observed, 33.85 expected, observed/expected ratio (o/e) 0.5, 90% interval 0.34 to 0.75. The synonymous counts are far from expectation, so gnomAD's model fits this gene poorly and the ratio says little. Missense variants: 605 observed, 701.06 expected, observed/expected ratio (o/e) 0.86, 90% interval 0.81 to 0.92. Synonymous variants: 498 observed, 341.58 expected, observed/expected ratio (o/e) 1.46, 90% interval 1.35 to 1.57.
Homologues: Orthologues: macaque FZD8 (99% identical), mouse Fzd8 (96% identical), rat Fzd8 (96% identical), pig FZD8 (93% identical), dog FZD8 (89% identical), chimpanzee FZD8 (79% identical), zebrafish fzd8a (70% identical), tropical clawed frog fzd8 (70% identical), zebrafish fzd8b (62% identical), Drosophila melanogaster fz3 (22% identical). Paralogues in human: FZD5 (58% identical), FZD2 (41% identical), FZD1 (40% identical), FZD7 (39% identical), FZD10 (38% identical), FZD9 (36% identical), FZD4 (34% identical), FZD3 (30% identical), FZD6 (29% identical), SMO (24% identical), FRZB (14% identical), SFRP4 (14% identical), and 3 more.
Diseases named in the same sentence as FZD8 in open-access papers:
FZD8 is named in the same sentence as 64 diseases in open-access papers, as found by Europe PMC text mining. Sharing a sentence is not in itself a finding about the gene and the disease. The quoted sentences say what the papers report.
prostate carcinoma (19 papers, 2018 to 2025). A carcinoma that arises from epithelial cells of the prostate gland. "QRT-PCR analysis revealed lower expression of the β-catenin, Fzd8, Wnt5a and cyclin D1 genes in prostate cancer compared to benign prostatic hyperplasia tissues." (PMID 41465498, 2025). "Previous studies have demonstrated that Fzd8 plays a promotive role in tumor cell proliferation and metastasis in renal and thyroid cancers, as well as contributes to bone metastasis in prostate cancer." (PMID 41465498, 2025). "Specifically, they reported that the unusual expression of FZD8 in prostate cancer resulted in the hyperactivation of Wnt signaling by triggering a positive feedback loop of Wnt3A, a ligand of the canonical pathway that causes bone metastasis." (PMID 34685470, 2021). "Mounting evidences showed that FZD8 was involved in various malignant tumors including prostate cancer, lung cancer, breast cancer, and gastric cancer." (PMID 33618667, 2021). "Aberrant expression of FZD8 has been reported in gastric cancer, prostate cancer, renal cell carcinoma, lung cancer, pancreatic adenocarcinoma, and overexpression of FZD8 was considered to promote tumor metastasis." (PMID 35116059, 2021). "Li and coworkers showed that FZD8 promotes prostate cancer migration through β-catenin and that FZD8 knockdown inhibited bone metastases, specifically." (PMID 34685470, 2021). "FZD8 is a downstream target of multiple oncogenes including ETS-related gene (ERG) in prostate cancer, SRC in lung adenocarcinoma, and Mesenchymal–Epithelial Transition (MET) in HNSCC." (PMID 34604862, 2021). "A recent report showed that crosstalk between the TGF-β and Wnt signaling pathways in prostate cancer cells is mediated by an interaction between the cysteine-rich domain of FZD8 and the extracellular domain of TGFBRI53." (PMID 32415058, 2020). "Here, we provide evidence that FZD8 is a major Wnt-11 receptor in prostate cancer that integrates Wnt-11 and TGF-β signals to promote EMT." (PMID 29717114, 2018). "FZD8 silencing reduces prostate cancer cell migration, invasion, three-dimensional (3D) organotypic cell growth, expression of EMT-related genes, and TGF-β/Smad-dependent signaling." (PMID 29717114, 2018). "These 3D cell culture data further support a role for FZD8 in promoting tumor cell invasion in prostate cancer." (PMID 29717114, 2018). "Stable FZD8 knockdown using two different lentiviral shFZD8 constructs also reduced prostate cancer cell invasion." (PMID 29717114, 2018). "Overexpression of FZD8 promoted, while silencing of FZD8 suppressed prostate cancer cell migration, invasion, stem cell-like phenotypes in vitro and bone metastasis in vivo by the activation of WNT/β-catenin signaling." (PMID 29789460, 2018). "Together, these results indicate that FZD8 contributes to the migratory and invasive activities of metastatic prostate cancer cells." (PMID 29717114, 2018). "FZD8 mRNA is upregulated in multiple prostate cancer datasets and in metastatic cancer cell lines in vitro and in vivo." (PMID 29717114, 2018). "Here the authors show that in prostate cancer cells Wnt11 signals through the Fzd8 receptor and report an interaction between Fzd8 and TGF-β receptors regulating the transcription of a subset of TGF-beta genes." (PMID 29717114, 2018). "Genes encoding FZD2-5, FZD8, VANGL1, ROR1, RYK, LGR4, LRP5 and 6, and GPC4 were highly expressed in at least three prostate cancer cell lines." (PMID 29717114, 2018). "Together, these data support a role for FZD8 in β-catenin-independent Wnt signaling in prostate cancer." (PMID 29717114, 2018).
prostate carcinoma (continued). "The authors' observations that FZD8 is upregulated in prostate cancer and promotes prostate cancer cell migration and invasion are consistent with ours." (PMID 29717114, 2018). "Our findings show that FZD8, like Wnt-11, is highly expressed in more aggressive prostate cancer cell lines." (PMID 29717114, 2018). "To validate the functional role of FZD8 in prostate cancer cells in vivo, we used the chorioallantoic membrane (CAM) model." (PMID 29717114, 2018). "These revealed a clear upregulation of FZD8 in prostate cancer, compared to normal prostate, and in prostate cancer metastases, compared to primary tumors." (PMID 29717114, 2018). "Furthermore, FZD8 knockdown in a chick chorioallantoic membrane (CAM) model of prostate cancer reduced tumor burden correlating with a reduction in vimentin expression." (PMID 35204808, 2022). "Moreover, Frizzled-8 receptor (FZD8) activated Wnt/β-catenin signaling promoted prostate cancer cell migration, invasion, and stem cell-like phenotypes in vitro, and enhanced bone metastasis in vivo." (PMID 35177982, 2021). "FZD8 may therefore be a useful therapeutic target in metastatic prostate cancer, since blocking its activity has the potential to inhibit aberrant activation of both Wnt and TGF-β signals." (PMID 29717114, 2018). "Further analysis indicated that elevated FZD8 and WNT11 expression was more prevalent in patients with recurrent disease, as compared to disease-free patients (p = 0.049, Fisher’s exact test, two-sided), supporting the relevance of WNT-11-FZD8 signaling to prostate cancer progression." (PMID 29717114, 2018). "Moreover, FZD8 was upregulated in the highest number of datasets when comparing prostate carcinoma and benign prostate." (PMID 29717114, 2018). "In keeping with the importance of Wnt signaling in tumor progression and EMT41, FZD8 silencing reduced mesenchymal gene and protein levels, which may account for its requirement for prostate cancer cell migration and invasion." (PMID 29717114, 2018). "Here, we have identified FZD8 is a major Wnt-11 receptor in prostate cancer that may be a useful therapeutic target." (PMID 29717114, 2018). "Analysis of the expression of vimentin, which contributes to prostate cancer invasiveness, indicated that tumors in which FZD8 was silenced exhibited lower levels of vimentin than control tumors, consistent with the role of FZD8 in prostate tumor cell invasion." (PMID 29717114, 2018). "Expression of FZD8 mRNA is also elevated in tumor samples of prostate cancer datasets." (PMID 29717114, 2018). "Also, miR-99-5p targets FZD8, which is known to reduce prostate cancer cell migration and invasion." (PMID 38132140, 2023). "In a recent study on long non-coding RNAs (lncRNAs), LINC00115 was shown to induce prostate cancer cell proliferation via the miR-212-5p/FZD5/Wnt/β-catenin axis, in which Fzd8 leads to the activation of the canonical Wnt pathway." (PMID 41465498, 2025). "For example, the activation of Wnt receptors FZD8 and LRP5 was reported to facilitate cell migration and invasion by accelerating EMT in prostate cancer." (PMID 34568020, 2021). "Wnt5a promotes liver fibrosis by FZD2 and FZD8 42, and Wnt11 binds to FZD8 known to be involved in TGF-β signaling in prostate cancer." (PMID 33391533, 2021). "In summary, our results suggest that by interacting with TGFβRI, FZD8 can coordinate Wnt and TGF-β signals to promote expression of EMT genes and increase prostate cancer cell migration and invasion." (PMID 29717114, 2018). "In contrast, FZD8 was upregulated in prostate tumor datasets, correlated with WNT11 expression in prostate cancer cell lines and FZD8 protein levels correlated with Wnt-11 in prostate TMAs." (PMID 29717114, 2018). "Taken together, these observations support a model in which FZD8, by interacting both with Wnt-11 and TGFβRI, is able to play a pivotal role in integrating Wnt and TGF-β signals to drive EMT and invasion in prostate cancer." (PMID 29717114, 2018).
prostate carcinoma (continued). "Consistent with the role of FZD8 as a Wnt-11 receptor, silencing of FDZ8 reduced prostate cancer cell migration and invasion." (PMID 29717114, 2018). "Our results showed lower expression of Wnt pathway-related proteins—β-catenin, Fzd8, Wnt5a and cyclin D1—in prostate cancer compared to BPH tissues, but the differences were not statistically significant." (PMID 41465498, 2025). "FZD8 is directly targeted and activated by ERG, which is involved in bone metastasis of prostate cancer by regulating Wnt-11 and TGF-β signaling to stimulate epithelial–mesenchymal transition in prostate cancer." (PMID 36579559, 2022). "In contrast, our results indicate that Wnt/β-catenin signaling activity is low in prostate cancer and is not affected by FZD8 silencing." (PMID 29717114, 2018). "Targeting FZD8 may therefore inhibit aberrant activation of both Wnt and TGF-β signals in prostate cancer." (PMID 29717114, 2018). "FZD4, FZD8, and PTK7, but not FZD2, were more highly expressed in prostate cancer than in benign or normal prostate tissue." (PMID 29717114, 2018).
breast carcinoma (9 papers, 2015 to 2021). "It has been reported that miR-100 can target FZD-8 and inhibit the Wnt/β-catenin signaling to inhibit the invasion and migration of breast cancer cells." (PMID 33194849, 2020). "Frizzled-8 receptor (FZD8) expression was significantly higher in human breast cancer tissues compared with the adjacent normal tissues, and higher expression of FZD8 was closely correlated with lymph node metastasis." (PMID 33488948, 2020). "MicroRNA-100 suppresses the migration and invasion of breast cancer cells by targeting FZD-8 and inhibiting T-cell factor-4 (TCF-4) expression." (PMID 31049030, 2019). "Many members of this module, including WIF1, WNT1, SFRP1, FZD9, and FZD8 were hypermethylated and underexpressed in both luminal-A and luminal-B breast cancers but exhibiting larger deviations in DNAm and mRNA expression in the luminal-B subtype." (PMID 26664652, 2015). "In addition, overexpression of FZD8 leaded to chemotherapy resistance in breast cancer patients." (PMID 35116059, 2021). "Together, these data suggested that Wnt/β-catenin signaling mediated through FZD8 and LRP6 plays a major role in human breast cancers, drug resistance and metastasis." (PMID 33488948, 2020).
lung cancer (9 papers, 2011 to 2021). A malignant neoplasm involving the lung. "Previous studies have demonstrated the upregulated expression of FZD8 in primary lung tumor, and knockdown of FZD8 inhibited the growth of lung cancer and make lung cancer cells sensitive to taxotere therapy." (PMID 29108281, 2017). "Finally, miR-99b-5p was shown to directly target Fzd8 in non–small-cell lung cancer, resulting in decreased cell proliferation, invasion, and migration during in vitro analysis." (PMID 34671643, 2021). "The epilepsy drug carbamazepine binds Fzd8 to suppress β-catenin signaling, and Fzd9 may be a critical receptor for a lung cancer chemoprevention drug." (PMID 34671643, 2021). "Through this pathway, mutation at and surrounding the β-catenin site is most common in cancers, but in regard to lung cancer, its distinguishing factor is based on alterations to various Wnt proteins including Wnt-1–5a, frizzled class receptor 8 (FZD8), and the gene β-catenin." (PMID 32316322, 2020). "In addition, recently FZD8 has been proposed to be a putative therapeutic target in human lung cancer." (PMID 23658834, 2013). "The association between lung cancer and 4 target genes (FZD8, LRP5, PIAS1 andRUNX1) has been previously reported.It has been reported that FZD8is highly expressed in A549 cell line and the dysregulation of FZD8 might play key roles in human cancer through activation of beta-catenin-TCF pathway." (PMID 26642205, 2015).
non-small cell lung carcinoma (6 papers, 2013 to 2022). A group of at least three distinct histological types of lung cancer, including non-small cell squamous cell carcinoma, adenocarcinoma, and large cell carcinoma. "The lncRNA AK126698 decreases the proliferation and migration of non-small cell lung cancer (NSCLC) cells through targeting FZD8 to inhibit the Wnt/β-catenin signaling pathway." (PMID 29108281, 2017). "OMP-18R5 (Vantictumab) targets the FZD1, FZD2, FZD5, FZD7, and FZD8 frizzled protein receptors to block WNT signaling are being investigated in phase I clinical trials in breast, pancreatic, and non-small cell lung cancer." (PMID 32758244, 2020).
gastric cancer (5 papers, 2019 to 2024). A primary or metastatic malignant neoplasm involving the stomach. "FZD1 and FZD8 as oncogenes promote the proliferation, invasion, and migration of gastric cancer cells, and high expression of FZD8 suggests that a patients has a poor prognosis." (PMID 38952556, 2024). "FZD8 in overexpressed in both intestinal metaplasia and gastric cancer tissues, suggesting alterations in FZD8 may occur early in progression and making it a potential target for chemoprevention in premalignant tissues." (PMID 34604862, 2021).
colorectal cancer (4 papers, 2016 to 2021). A primary or metastatic malignant neoplasm that affects the colon or rectum. "Specifically, we found that a subgroup of seven genes – BIRC5, CYCS, FZD3, FZD8, MAPK9, SMAD3, and SOS1 – that belong to the KEGG colorectal cancer pathway showed significant association with risk of BCC." (PMID 27367190, 2016).
pancreatic cancer (4 papers, 2014 to 2021). "FZD5 and FZD8 have roles in early development in both pancreatic cancer and acute myeloid leukemia." (PMID 34604862, 2021). "Ipafricept (OMP-54F28) is a FZD8 decoy receptor that binds WNTs and has been tested as both a monotherapy in solid tumors and dual therapy for HCC, ovarian cancer, and pancreatic cancer." (PMID 34604862, 2021).
renal cell carcinoma (4 papers, 2017 to 2025). "Renal cell carcinoma (RCC) tissues have been demonstrated to have considerably increased levels of FZD5 and FZD8 mRNA." (PMID 40171220, 2025). "FZD8 plays a role in tumor initiation, invasion, and metastasis in various cancers, including head and neck squamous carcinoma (HNSCC), gastric, breast, NSCLC, thyroid, cervical, renal cell carcinoma (RCC), and prostate." (PMID 34604862, 2021).
triple-negative breast carcinoma (4 papers, 2016 to 2025). An invasive breast carcinoma which is negative for expression of estrogen receptor (ER), progesterone receptor (PR), and human epidermal growth factor receptor 2 (HER2). "FZD8 regulated Wnt signaling play a crucial role in promoting resistance to chemotherapy in the triple-negative breast cancer (TNBC)." (PMID 29108281, 2017). "Additionally, FZD8 activation of Wnt signaling contributes to chemoresistance in triple-negative breast cancer." (PMID 40430278, 2025). "Moreover, FZD8-mediated Wnt/β-catenin signaling appeared to participate in mediating resistance to chemotherapy in triple-negative breast cancer." (PMID 27276676, 2016). "In triple-negative breast cancer (TNBC), the knockdown of FZD8 results in enhanced apoptosis with down-regulated β-catenin and survivin expression, and sensitizes the TNBC cells to chemotherapy, such as cisplatin plus TRAIL." (PMID 29108281, 2017).
thyroid cancer (3 papers, 2018 to 2022). "CircRNA_NEK6 facilitates thyroid cancer progression by sponging miR-370-3p and upregulating the FZD8/Wnt axis." (PMID 35513849, 2022). "CircRNA_NEK6 activated the FZD8/Wnt axis to facilitate thyroid cancer progression by sponging miR-370-3p." (PMID 35513849, 2022). "CircNEK6 targeting miR-370-3p promoted the disease progression by up-regulating FZD8, and activating Wnt signaling pathway in thyroid carcinoma." (PMID 30540564, 2018). "In thyroid cancer, miR-370-3p is sponged by other ncRNAs, leading to increased Fzd8 expression." (PMID 34671643, 2021). "Fzd8 and NEK6 are overexpressed in thyroid cancer, where NEK6 is a circRNA that targets miR-370-3p, which targets Fzd8 3′UTR." (PMID 34671643, 2021).
acute lymphoblastic leukemia (2 papers, 2017 to 2022). Leukemia with an acute onset, characterized by the presence of lymphoblasts in the bone marrow and the peripheral blood. "FZD7 and FZD8 are expressed in most acute lymphoblastic leukemia (ALL) cells, while FZD3, FZD4, and FZD9 are occasionally detected." (PMID 36452482, 2022).